PTH (parathyroid hormone)
Diseases named in the same sentence as PTH in open-access papers (continued):
Sharing a sentence is not in itself a finding about the gene and the disease.
Hypercalcemia (continued). "Similarly, murine models revealed that PTH infusion and consequent hypercalcemia were associated with higher glucose levels and similar insulin levels, while both PTH and calcium positively correlated with glucose levels only in rats who received PTH injections." (PMID 40283231, 2025). "Hypercalcemia and a decrease in PTH may be associated with decreased blood pressure." (PMID 38613076, 2024). "Cardiovascular changes might be caused, not only by hypercalcemia, but also by high PTH levels, considering that PTH may induce vasodilation, is associated with a positive ionotropic and chronotopic effect, and promotes hypertrophic growth of the cardiac myocytes." (PMID 39518465, 2024). "Therefore, we hypothesized that the hypercalcemia was caused by the PTH-rp production in her giant myoma, which could be stimulated by the estrogen levels in pregnancy." (PMID 39148641, 2024). "Hypercalcemia of malignancy is usually caused by osteolytic processes of metastases, production of parathormone-related peptide, or secretion of 1,25-dihydroxyvitamin D. Here, we present a case of ectopic PTH production by malignancy and have identified further 11 published cases in the literature." (PMID 39703837, 2024). "Fever of unknown origin remains a challenging diagnostic entity, and parathyroid carcinoma, though rare, should be considered a differential diagnosis in patients presenting with FUO, particularly when associated with significant hypercalcemia, elevated parathyroid hormone levels, and neck masses." (PMID 39822449, 2024). "Indeed, tyrosine kinase inhibitors may lead to hypophosphatemia and increased parathyroid hormone levels, with low–normal calcium levels, while immune checkpoint inhibitors may cause hypocalcemia and hypercalcemia." (PMID 36672478, 2023). "Furthermore, a decline in renal function due to hypercalcaemia decreases phosphorus excretion, which compromises the calcaemic action of PTH due to a loss of parathyroid gland sensitivity to the control by serum concentrations of calcium and phosphorus due to an increase in serum phosphorus." (PMID 36515670, 2022). "In addition, other factors contribute to the presence of hypercalcemia,such as resorption of vascular and ectopic calcifications, prolonged postoperativeimmobility, and abrupt discontinuation of post-KTx cinacalcet, which, associatedwith high PTH levels, can lead to severe hypercalcemia." (PMID 34910805, 2021). "However, we suggest that the longer time on HD, hypercalcemia, hyperphosphatemia and elevated PTH level may be associated with the high prevalence of gallstones in the HD patients with advanced SHPT on cinacalcet." (PMID 29301445, 2018). "Thus, these sympathetic-mediated changes in CT and PTH secretion may cause hypercalcemia and bone loss." (PMID 28713236, 2017). "The medical records of the remaining 72 patients who had either a normal or low PTH level were reviewed to further exclude specific causes of hypercalcemia, and to evaluate whether the presentation and the clinical and biochemical features of individual patients could be attributable to CSS." (PMID 26239247, 2015). "The hypercalcemia was associated with a higher urinary calcium excretion rate, consistent with delivery of a higher filtered calcium load to the renal tubules and the decreased renal tubular reabsorption of calcium that would result from the reduced circulating PTH concentrations." (PMID 24302625, 2014). "In 85% of cases, PHPT is asymptomatic and is diagnosed following hypercalcemia and elevated PTH levels during routine examinations." (PMID 41568160, 2026). "Hypercalcemia, hypophosphatemia, and elevated PTH are the characteristic features and pathophysiology of GPA." (PMID 41473886, 2026). "PHPT is most often asymptomatic and quickly diagnosed in the presence of hypercalcemia and elevated PTH levels." (PMID 41568160, 2026). "Initial laboratory investigations revealed parathyroid hormone (PTH)-independent hypercalcaemia and renal impairment." (PMID 41700239, 2026).
Hypercalcemia (continued). "In this clinical case an analysis of clinical, laboratory and instrumental data revealed a rare combination of PTH-dependent and PTH-independent hypercalcemia." (PMID 41640160, 2026). "We report a diagnostically complex case of sarcoidosis presenting with massive splenomegaly, pancytopenia, parathyroid hormone-independent hypercalcemia with renal dysfunction, and bone marrow findings suggestive of myelodysplastic syndrome." (PMID 42158759, 2026). "Acute pancreatitis secondary to hypercalcemia was diagnosed, and normal parathyroid hormone (PTH) levels excluded primary hyperparathyroidism." (PMID 41939661, 2026). "Primary hyperparathyroidism (PHPT) is a metabolic disorder characterized by hypercalcemia with elevated or unsuppressed parathyroid hormone (PTH)." (PMID 41568160, 2026). "We report a case of a man who returned from a sunny holiday in Portugal with abdominal symptoms, confusion, and severe hypercalcaemia with normal serum parathyroid hormone (PTH)." (PMID 42281697, 2026). "We present the case of a 57-year-old woman with hypercalcemia, hypercalciuria, and inappropriately normal parathyroid hormone (PTH) levels." (PMID 42027586, 2026). "The final case featured a 47-year-old man with severe symptomatic hypercalcemia (18.5 mg/dL) and markedly elevated PTH." (PMID 41899334, 2026). "HPHPT chief cell patterns show a marked CaSR decreased expression along with an increased CYP27B1/VDR expression, suggesting an appropriate autocrine/paracrine counterregulation to hypercalcemia/high PTH." (PMID 41907687, 2026). "Case Presentation: A 74-year-old woman with fragility fractures, generalized bone pain, and nephrolithiasis was initially diagnosed with primary hyperparathyroidism due to concomitant hypercalcemia, hypophosphatemia, and elevated parathyroid hormone (PTH)." (PMID 42279228, 2026). "Laboratory studies revealed hypercalcemia (10.9 mg/dl), markedly elevated parathyroid hormone (PTH) (1235 pg/ml), hypophosphatemia, vitamin D insufficiency, and hypomagnesemia." (PMID 42006526, 2026). "Together, these cases highlight that symptomatic severe hypercalcemia is a medical emergency warranting prompt clinical intervention, followed by an early PTH-based stratification to direct a focused, stepwise diagnostic workup and definitive management." (PMID 41899334, 2026). "Laboratory data during these admissions showed PTH level of 311 pg/mL (normal range 12–88 pg/mL) and uptrending hypercalcemia of 14.5 mg/dL (normal range 8.6–10.2 mg/dL)." (PMID 41502796, 2026). "Still, after surgical removal of the suspected adenoma with an intraoperative parathyroid hormone decrease of >50%, severe hypercalcemia recurred quickly." (PMID 42302384, 2026). "This case underscores the importance of urinary calcium assessment and genetic testing in PTH-dependent hypercalcemia and highlights a potential therapeutic role for cinacalcet in selected FHH2 patients." (PMID 42291983, 2026). "Laboratory tests revealed severe hypercalcemia with elevated PTHrP and suppressed parathyroid hormone levels." (PMID 41567516, 2026). "In contrast to adult PHPT, which is often detected incidentally, pediatric patients are frequently symptomatic at diagnosis, with manifestations reflecting prolonged exposure to hypercalcemia and elevated parathyroid hormone levels." (PMID 41750717, 2026). "Biological tests showed corrected hypercalcemia at 3.07 mmol/L, phosphatemia at 0.93 mmol/L, calcemia/phosphoremia ratio is 3.3, elevated PTH at 2613 pg/mL, elevated alkaline phosphatase at 3669 IU, and a deficiency in 25‐hydroxyvitamin D3 at 7.1 ng/mL." (PMID 41568160, 2026). "Diagnosis of primary hyperparathyroidism (PHPT) relies on the detection of hypercalcemia and increased circulating parathormone (PTH) levels." (PMID 41752149, 2026). "Biochemical tests confirmed hypercalcemia and elevated parathyroid hormone from a parathyroid adenoma." (PMID 42117028, 2026).
Hypercalcemia (continued). "The second case describes a 30-year-old woman who presented with hypotension, hypercalcemia, hyperphosphatemia, and low PTH." (PMID 41899334, 2026). "We report a case of PHPT diagnosed during fracture workup in a female patient who manifested persistent hypercalcemia and elevated parathyroid hormone (PTH) despite two prior cervical explorations." (PMID 41884128, 2026). "Biochemistry showed severe hypercalcemia with strikingly elevated parathyroid hormone and alkaline phosphatase; imaging demonstrated diffuse osteopenia and localized enlarged parathyroid glands." (PMID 41878601, 2026). "PHPT caused by nongiant PA usually is accompanied by asymptomatic hypercalcemia and enhanced PTH, while according to studies, hypercalcemia and increased PTH are clearly detectable in GPA." (PMID 41473886, 2026). "During admission, she developed acute confusion and was found to have severe hypercalcemia (albumin-corrected calcium 3.7 mmol/L) with suppressed parathyroid hormone (PTH) and elevated parathyroid hormone-related protein (PTHrP)." (PMID 42281681, 2026). "Laboratory studies demonstrated hypercalcemia with elevated parathyroid hormone levels, consistent with PHPT, with preserved renal function and concurrent vitamin D insufficiency." (PMID 42306171, 2026). "Laboratory evaluation typically reveals an elevated serum calcium level with suppressed parathyroid hormone (PTH) consistent with a parathyroid hormone-related peptide (PTHrP)-mediated hypercalcemia." (PMID 40896427, 2025). "Four mechanisms are responsible: Local osteolysis, humoral hypercalcemia driven by parathyroid hormone‐related protein (PTH‐rP), hypercalcemia mediated by 1.25‐dihydroxyvitamin D, and ectopic hyperparathyroidism, though the latter two are rare." (PMID 40067281, 2025). "Our patient presented with acute severe asymptomatic hypercalcemia with paired corrected calcium of 3.50 mmol/L (14 mg/dL) (reference 2.1-2.6 mmol/L [8.4-10.4 mg/dL]) and PTH of 1.1 pmol/L (10.4 pg/mL) (reference 1.6-6.9 pmol/L [15.1-65.1 pg/mL])." (PMID 39906901, 2025). "In the current study, 45 consecutive pHPT patients with hypercalcemia and elevated parathyroid hormone levels were assessed clinically, biochemically and by 24-h ECG monitoring before, one and six months after curative parathyroidectomy (PTX)." (PMID 40771273, 2025). "During a routine follow-up, the patient was found to have hypercalcemia, elevated parathyroid hormone levels, and increased serum creatinine." (PMID 40182382, 2025). "Our patient presented with persistent hypercalcemia, significantly elevated PTH levels, and a giant cyst of uncertain originall valid indications for surgical excision." (PMID 41383495, 2025). "Only after repeated admissions, elevated fasting gastrin levels, and biochemical evidence of hypercalcemia with raised parathyroid hormone (PTH) was MEN1 suspected and subsequently confirmed on genetic testing." (PMID 41541958, 2025). "PHTP is typically characterized by the combination of hypercalcemia and elevated, or inappropriately high, PTH levels." (PMID 40870022, 2025). "Up to 80% of patients with PHPT, characterized by hypercalcemia and elevated or inappropriately high levels of parathyroid hormone (PTH) relative to circulating calcium levels, are asymptomatic." (PMID 41156271, 2025). "Initial biochemical laboratory tests revealed elevated PTH (parathyroid hormone), hypercalcemia, hyperphosphatemia and elevated creatinine." (PMID 40922257, 2025). "While primary hyperparathyroidism (PHPT) represents the most common etiology of PTH-dependent hypercalcemia, familial hypocalciuric hypercalcemia (FHH) constitutes a distinct genetic disorder." (PMID 40417236, 2025). "The opposite reaction was seen in serum PTH, where men with hypercalcemia had a decrease in PTH from 1.0 pmol/L (SD 0.7) at baseline, to 2.1 pmol/L (SD 2) after 48 months, with a significant difference (p < 0.001) when compared to men with normocalcemia." (PMID 40353949, 2025).
Hypercalcemia (continued). "Our patient presented with persistent hypercalcemia in the setting of suppressed PTH, which effectively excluded primary hyperparathyroidism." (PMID 41487858, 2025). "Primary hyperparathyroidism (PHPT) is a common endocrine disorder characterized by excessive and autonomous secretion of parathyroid hormone (PTH) by one or more parathyroid (PT) glands, resulting in asymptomatic or symptomatic hypercalcemia." (PMID 40149663, 2025). "This case highlights the diagnostic complexity and the importance of an interdisciplinary approach in managing rare conditions like lactational hypercalcemia and ectopic PTH secretion in the postpartum period." (PMID 41487858, 2025). "Discontinuation of lithium resulted in normalisation of calcium levels, confirming lithium-induced hypercalcaemia in the context of normal parathyroid hormone (PTH) levels." (PMID 41185877, 2025). "PHPT is characterized by excessive and inappropriate secretion of endogenous PTH by 1 or more parathyroid glands, resulting in hypercalcemia because of a concomitant defective feedback control of PTH secretion by extracellular calcium concentrations." (PMID 40177730, 2025). "Determination of 1,25(OH)2D is very useful in diagnosing of PTH-independent hypercalcaemia related with ectopic synthesis of 1,25(OH)2D in granulomatous disease like sarcoidosis, tuberculosis, Crohn disease and lymphoproliferative disorders." (PMID 40502410, 2025). "After kidney transplantation, uremia subsides, allograft function readily activates 25(OH)D, and persistent parathyroid autonomy meets resolving PTH resistance of bone stores resulting in transient or persistent hypercalcemia." (PMID 41303180, 2025). "Laboratory tests revealed hypercalcemia and elevated PTH, while abdominal ultrasound showed nephrocalcinosis." (PMID 40666157, 2025). "The first shift moved beyond simple calcitriol replacement with the development of selective vitamin D receptor activators (VDRAs) designed to minimize hypercalcemia while maximizing PTH suppression." (PMID 41515987, 2025). "First, suppressed PTH in the presence of hypercalcemia warrants consideration of ectopic PTH/PTHrP secretion, even in the postpartum setting." (PMID 41487858, 2025). "High levels of PTH after this period are responsible for hypercalcemia and hypophosphatemia and define THPT." (PMID 41301699, 2025). "Hypercalcemia typically results from parathyroid hormone (PTH)–enhanced renal tubular calcium reabsorption, calcitriol–mediated gastrointestinal calcium absorption, and potential PTH–induced bone calcium release." (PMID 41036144, 2025). "As the predominant etiology of hypercalcemia, PHPT results from abnormal, dysregulated PTH secretion, with approximately 80% of cases are caused by solitary parathyroid adenoma." (PMID 41272807, 2025). "Our aim in this case report is to present a rare phenomenon of lithium-induced hypercalcaemia with normal serum PTH levels." (PMID 41185877, 2025). "The people suffering from depression and hypercalcemia had lower odds of having a PTH check-up [OR = 0.84 (0.74, 0.96), p = 0.0081], suggesting a potential testing gap on this specific matter (Table A1)." (PMID 39997061, 2025). "A positive culture/staining of NTM, acute renal failure, low PTH, or normal/high 1,25(OH)2D suggests hypercalcemia etiology." (PMID 40284609, 2025). "The most common etiology of hypercalcemia in patients with elevated PTH levels is primary hyperparathyroidism, usually due to a parathyroid adenoma." (PMID 41210046, 2025). "Primary hyperparathyroidism (PHPT) represents one of the most frequent endocrine conditions, defined by excessive parathyroid hormone (PTH) secretion, resulting in hypercalcemia and hypophosphatemia." (PMID 41163950, 2025). "Laboratory evaluation revealed severe hypercalcemia (15.1 mg/dL), suppressed parathyroid hormone (4.2 pg/mL), and elevated parathyroid hormone-related peptide (83 pg/mL)." (PMID 40337388, 2025).
Hypercalcemia (continued). "Careful monitoring of vitamin D, calcium, and PTH levels is recommended to personalize therapy, maximize benefits, and minimize risks such as hypercalcemia or ectopic calcification." (PMID 41516172, 2025). "Primary hyperparathyroidism is a well-documented clinical condition, characterized by asymptomatic hypercalcemia and elevated levels of parathyroid hormone (PTH), with the most common etiology being parathyroid adenoma." (PMID 41210046, 2025). "Given the findings, the differential diagnosis for non-PTH-mediated hypercalcemia included lymphoma, sarcoidosis, and lung malignancy." (PMID 40400876, 2025). "Blood results will be consistent with HPT and will show hypercalcemia, hypophosphatemia, and increased levels of PTH and alkaline phosphatase." (PMID 41503329, 2025). "The diagnosis of PHPT requires biochemical analysis revealing simultaneous hypercalcemia an elevated PTH levels (or inappropriately normal levels)." (PMID 40149663, 2025). "Subsequent investigations were done and revealed hypercalcemia [serum calcium of 18 mg dL-1, ionized calcium (iCa2+) 4.08 mmol L-1, serum PTH 971 pg mL-1 (range 15-65 pg mL-1)], and hyperkalemia (serum potassium 6.3 mEq L-1)." (PMID 40150828, 2025). "Primary hyperparathyroidism (PHPT) is a common endocrine disorder characterized by excessive parathyroid hormone secretion, leading to hypercalcemia and a spectrum of end-organ complications, including nephrolithiasis and chronic kidney disease (CKD)." (PMID 41438725, 2025). "Our index patient initially presented with a classical picture of pHPT, including hypercalcemia, an inappropriately normal PTH concentration, and a sonographically and histologically confirmed parathyroid adenoma." (PMID 41009532, 2025). "Medications such as thiazide diuretics and lithium can also contribute to hypercalcemia by reducing Ca excretion or increasing parathyroid hormone (PTH) secretion." (PMID 39940312, 2025). "It typically presents with pronounced hypercalcemia and markedly elevated parathyroid hormone (PTH) levels." (PMID 41465801, 2025). "Hypoparathyroidism was most common (n = 7), followed by PTH resistance (n = 3), hyperparathyroidism (n = 1), calcipenic rickets (n = 1), and syndromic hypercalcemia (n = 1)." (PMID 41155848, 2025). "PHP, often caused by a single adenoma (80-85% of cases), is characterised by excessive PTH secretion, leading to hypercalcaemia and complications such as nephrolithiasis, skeletal fragility, and neuropsychiatric symptoms." (PMID 41384172, 2025). "Clinically, PC is characterized by markedly elevated PTH levels and significant hypercalcemia, leading to a spectrum of symptoms that range from mild fatigue and nausea to severe complications such as renal failure and pathological fractures." (PMID 41465801, 2025). "In a cohort study where 849 patients were followed 1 year after a kidney transplant, 21.5% of them developed THPT, defined by elevated PTH levels (>70 pg/mL) and hypercalcemia (>10 mg/dL)." (PMID 41301699, 2025). "PHPT was characterized by elevated PTH, which induced hypercalcemia and hypophosphatemia through multifactorial mechanisms." (PMID 41561737, 2025). "The laboratory tests showed anemia, hypercalcemia with suppression of parathyroid hormone (PTH) levels, hypoproteinemia, and kidney failure." (PMID 39758152, 2025). "Laboratory blood tests revealed an elevated PTH level – 216 pg/mL (15–65 pg/mL), hypercalcemia – 2.7 mmol/L (2.15-2.55 mmol/L), and 25(OH)vitamin D deficiency." (PMID 41323978, 2025). "Surgery frequently leads to the normalization of blood calcium and PTH levels; therefore, removing the consequences of hypercalcemia such as pancreatitis." (PMID 41001160, 2025). "The individual threshold at which hypercalcemia emerges depends on multiple factors, including kidney function, calcium intake, PTH levels, and bone metabolic turnover capacity." (PMID 41303180, 2025).